POLE (DNA polymerase epsilon, catalytic subunit)
Diseases named in the same sentence as POLE in open-access papers (continued):
Sharing a sentence is not in itself a finding about the gene and the disease.
tumor (continued). "Visual inspection of the number of unfiltered somatic variants per sample identified six grade 3 endometrioid samples with high tumor mutational burden, all of which demonstrated POLE mutations, most commonly P286R and V411L." (PMID 33256706, 2020). "Mutations in POLE and the levels of tumor mutation burden also appear as possible biomarkers of response to immunotherapy in CRC." (PMID 36046264, 2020). "In the remaining sample with POLE mutation and high tumor mutational burden, we identified a stoploss mutation at position 2287, near the 3′ end of the gene and outside of the known functional domains." (PMID 33256706, 2020). "In our cohort, the mean age of POLE-mutated tumours was 60.1 years versus 66.5 years in non-POLE mutated tumours." (PMID 30917185, 2019). "This mutational signature overlaps COSMIC signature SBS14, which has been associated with tumours with concurrent impairments of POLE and MMR functions." (PMID 31480372, 2019). "Patients with POLE-mutated tumours had a significantly better PFS and OS (og-rank results of 0.025, 0.147, and 0.023 respectively)." (PMID 30917185, 2019). "POLE/POLD1 gene variants have been suggested as potential markers for immunotherapy due to their significant association with the tumor mutational burden (TMB), an effective indicator for response prediction in immunotherapy." (PMID 31673068, 2019). "Tumors with POLE mutations were identified as one of the subgroups and represented an ultra-mutated tumor phenotype." (PMID 31866764, 2019). "POLE mutations have been demonstrated in an extensive number of tumor types that have shown sensitivity to checkpoint inhibitors." (PMID 31645345, 2019). "In conjunction with germline MMR-D, POLE mutations strongly increase the number of gene mutations in affected tumor cells." (PMID 31581674, 2019). "Both POLE-mutant and MMRd ECs contain a high mutational burden which elicits an increased immune response by tumor infiltrating lymphocytes (TIL)." (PMID 31367798, 2019). "From the KS cohort, information on ploidy shows that POLE-mutated tumours are significantly more often aneuploid than non-POLE-mutated tumours." (PMID 30917185, 2019). "Mutations in the exonuclease domain of the DNA polymerase epsilon (POLE) gene define one such subtype, which causes an ultra-mutated tumour phenotype." (PMID 30917185, 2019). "NF2 and POLE driver mutations were each present in 13 (34%) and 12 (32%) of the 38 total primary and recurrent tumor samples, respectively." (PMID 31191822, 2019). "POLE-mutated tumours are described as having excellent outcome, even in high-grade endometrioid histology, usually known to be associated with a more aggressive tumour." (PMID 30917185, 2019). "This confirms the results from the other published large cohorts showing that POLE mutated tumours are more often endometrioid and high grade." (PMID 30917185, 2019). "WGS was performed on his primary cancer revealing a hypermutated tumor, including clonal ultraviolet radiation-induced mutational patterns (Signature 7) and subclonal signatures of mutated DNA polymerase epsilon (POLE) (Signature 10)." (PMID 31645345, 2019). "Cohorts have been published from Vancouver, subgroups of PORTEC-1 and 2, the TCGA, Ohio, Calgary, Singapore, and combined PORTEC-NGO, presenting a total of over 150 POLE-mutated tumours with good to excellent survival rates." (PMID 30917185, 2019). "This study presents the phenotypic and mutational spectrum of a large cohort of POLE-mutated tumours." (PMID 30917185, 2019). "Patients with POLE-mutated tumours were significantly younger at the time of diagnosis than patients with non-POLE-mutated tumours (60.1 vs 66.5 years; p = 0.000)." (PMID 30917185, 2019). "Some of these mutations have been designated as “pathogenic” by other authors and tumours have been included in “POLE-mutated” groups based on them." (PMID 30917185, 2019).
tumor (continued). "Patients with a POLE-mutated tumour were significantly younger, were more often nulliparous, and had a history of smoking." (PMID 30917185, 2019). "The individualized treatment of tumors is closely related with the molecular typing of tumor genes, and tumor with the POLE gene mutation, representing a unique subtype of EC, owns a quite better prognosis." (PMID 31552169, 2019). "Ultra-mutated tumours with POLE mutations were identified as one of the four proposed molecular subgroups in a publication of The Cancer Genome Atlas (TCGA) based on their integrated genomic, transcriptomic, and proteomic characterization of 373 cases of EMCA." (PMID 30917185, 2019). "In analysis of the PFS and DSS, the hotspot POLE-mutated tumours do have a significantly better outcome; this finding confirms previously published data that POLE mutated tumours have a good outcome." (PMID 30917185, 2019). "The data show that patients with POLE-mutated tumours were significantly more often smokers or ex-smokers (p = 0.041)." (PMID 30917185, 2019). "Data on ploidy of the tumours were available for the KS cohort only; for this cohort, the POLE-mutated tumours were significantly more often aneuploid." (PMID 30917185, 2019). "In particular, isolated MMR deficiency and microsatellite instability have been mostly restricted to hyper-mutated tumours (TML between 10 and 100 muts/Mb), while ultra-mutated tumours (>100 muts/Mb) are microsatellite stable and POLE mutated." (PMID 31480372, 2019). "This also is consistent with a previous report that the EC patients with POLE mutation elicited anti-tumor immune response." (PMID 31645905, 2019). "In summary, we show that pathogenic, somatic POLE mutations are early, quite possibly initiating, events in sporadic cancers, and strongly shape subsequent tumour evolution." (PMID 29604063, 2018). "In these genes, the biased mutation patterns were detected in all POLE category tumours with POLE p.P286R or p.V411L." (PMID 29880869, 2018). "Tumours with somatic POLE exonuclease domain mutations are notable for their extreme genomic instability (their mutation burden is among the highest in human cancer), distinct mutational signature, lymphocytic infiltrate, and excellent prognosis." (PMID 29604063, 2018). "The mutations in ARID1A and POLE, and the fact that they were somatic, were confirmed by Sanger sequencing of DNA of tumor and normal tissues from the corresponding patients." (PMID 29599905, 2018). "To further characterise POLE-category tumours, we investigated pathways accumulating POLE-category-specific mutations between our data and ICGC data sets." (PMID 29880869, 2018). "To identify genes susceptible to POLE mutant effects, we counted the mutation patterns in individual tumours." (PMID 29880869, 2018). "Our classification showed that the sequential shift of mutation profile in genes had occurred in POLE-category tumours owing to the propensity of the POLE mutant effect." (PMID 29880869, 2018). "In contrast, MMR‐P and MMR‐D tumours rarely showed evidence of the POLE consensus mutational signature." (PMID 29604063, 2018). "The RPE1 spectrum differs markedly from the HT115 spectrum (cosine similarity = 0.67 ± 0.015) and the POLE mutant clinical tumor spectra and COSMIC mutation signature analysis." (PMID 30459213, 2018). "In conclusion, the present study identified hypermutator tumours harbouring POLE mutation from among over 2,000 Japanese patients with cancer, and showed the similarity of observed molecular profile to that of previous studies." (PMID 29880869, 2018). "The number of mutations (per Mb) in POLE-category tumours was significantly higher than in common hypermutators (p = 1.14 × 10−2 by Welch’s t-test)." (PMID 29880869, 2018).
tumor (continued). "Our analysis revealed that HR repair activity based on gene expression was increased in POLE-category tumours despite the occurrence of PTEN mutations as an early event in tumourigenesis." (PMID 29880869, 2018). "In this retrospective study, we initially analyzed genetic mutations in the POLE gene, evaluated tumor MSI status, MLH1 promoter methylation profile, and MMR expression status in all 138 ECs." (PMID 29659608, 2018). "Further, mutations in mismatch repair genes, homologous recombination genes, or POLE accurately predicted increased tumor mutational burden, neo-antigen load, and T cell infiltration." (PMID 29487705, 2018). "The sequential mutation shift of genes that accumulated in tumours with POLE mutants were then classified into three periods." (PMID 29880869, 2018). "Reanalysis of these discordant cases using Sanger sequencing revealed concordant findings among the three tumour blocks for POLE mutation status." (PMID 28424422, 2017). "Multi-tumour phenotypes such as colon/pancreas/ovaries/small intestine and colon/ovarian/endometrial/brain have been seen in POLE mutation carriers." (PMID 28331556, 2017). "Whole-exome sequencing (WES) was also performed in the tumor DNA of the patient carrying the POLE p.Val474Ile variant to study the number and spectrum of somatic mutations." (PMID 28423643, 2017). "POLE mutations were observed in many tumor types: endometrium/uterus, large bowel, ovary, pancreas, and breast." (PMID 28870239, 2017). "One tumor (T286) presented one POLE missense mutation (c.857C>G, p.Pro286Arg), and another tumor (T368) presented two POLE missense mutations (c.901G>A, p.Asp301Asn; and c.1376C>T, p.Ser459Phe)." (PMID 29072370, 2017). "In this regard, it is also worth mentioning that previous reports regarding POLE tumor mutation profile were generated mostly by using gene panel sequencing and with much higher coverage than the one used in the present study." (PMID 28423643, 2017). "Across the cohort, functional mutations in these mismatch repair genes and DNA polymerase occur in 13.5% of the cases with high TMB (858 cases with known functional mutations in mismatch repair or POLE out of the 6348 cases with high tumor mutation burden)." (PMID 28420421, 2017). "We searched for mutations in the exonuclease domain of the POLE gene (exons 9–14) in tumor DNA samples from 307 CRCs." (PMID 29072370, 2017). "Recently, some CRC patients with deficient MMR system caused by tumor biallelic inactivation were reported to also carry germline mutations in POLE, these MMR somatic mutations being the consequence of the POLE hypermutator tumor phenotype." (PMID 28423643, 2017). "Of the POLE‐mutated CRCs, one tumor was microsatellite‐stable and the other had low microsatellite instability, whereas KRAS and PIK3CA mutations were found in one tumor each." (PMID 29072370, 2017). "As is typical for POLE mutated tumors, this tumor was generally diploid with few regions of allelic imbalance and few genes focally amplified or deleted." (PMID 25808843, 2015). "This is despite a strong association of POLE proofreading mutations with high tumor grade—a characteristic that predicts a high risk of metastases in early EC." (PMID 25505230, 2015). "We subsequently demonstrated that somatic POLE proofreading mutations are found in about 7% of sporadic ECs, where they strongly associate with high tumor grade." (PMID 25505230, 2015). "Somatic mutations in the POLE gene encoding the catalytic subunit of DNA polymerase ɛ have been found in sporadic colorectal cancers (CRCs) and are most likely of importance in tumour development and/or progression." (PMID 24788313, 2014).
tumor (continued). "We performed individual MMR gene and combined dMMR survival stratification, multivariable Cox regression adjusted for age, histology, and sample type, and a pathogenicity-aware sensitivity analysis for POLE variants, with tumor mutational burden (TMB) compared across subgroups." (PMID 42195047, 2026). "POLE mutant ECs usually present with early lesions, high tumor grade, but showed a better prognosis, which is closely associated with the immune response, which warrants further novel immunotherapeutic explorations for POLE mutant EC." (PMID 39931062, 2025). "In addition, immunohistochemical staining for PD-L1 showed that higher PD-L1 expression in patients with POLE mutations than in WT patients, suggesting a potential mechanism of immune evasion by the tumor cells." (PMID 39931062, 2025). "Synergistic transcriptomic and proteomic analyses revealed that POLEP286R mutation-specific T cells significantly activated tumor- and immune-related signaling pathways upon recognition of POLE neoantigens, further confirming the possibility of neoantigen production by mutations at this locus." (PMID 39931062, 2025). "A less favored hypothesis is that intrinsically defective DNA repair related to POLE mutations makes tumor cells more susceptible to standard chemotherapy, although in vitro data showed platinum resistance rather than susceptibility." (PMID 40936703, 2025). "Eight MSI-H cancers and one pathogenic POLE mutation (V411L) were identified, which made up 30% of all hypermutated tumours and had a significantly higher TMB compared to the other samples; median 42.5 (34.0–56.5) versus 5.1 (3.9–7.2) mutations/Mb (p < 0.001), respectively." (PMID 40702107, 2025). "The five POLE mutation hotspots were associated with an elevated tumor mutational burden (TMB = 268 mut/Mb), which varied between different mutational hotspots (range 37.5-791.9 mut/Mb) and between tumors with identical hotspot mutations (e.g. P286R: 41.9-550.1 mut/Mb)." (PMID 40936703, 2025). "Moreover, POLE mutant ECs have a high tumor mutational burden (TMB) and increased lymphocyte infiltration, which is closely associated with immunotherapy response." (PMID 39931062, 2025). "Additionally, our study revealed that POLE mutations significantly enhanced cGAS expression level in primary human cells and tumor specimens." (PMID 38238314, 2024). "Moreover, the mutation of POLE would increase the tumor mutation burden by a high rate of base substitutions, which further enhanced the tumor immunogenicity." (PMID 39007151, 2024). "The 3-nucleotide sequence contexts of the POLE variants in Group 3 tumors strongly suggest that the POLE ExoD driver mutation first made the DNA synthesis error, and the cells with the additional POLE variant subsequently proliferated and expanded during tumor development." (PMID 38282550, 2024). "Broader panels with the ability to analyze hundreds of genes can indeed identify a greater number of druggable molecular alterations, define the tumor mutational burden, and detect increasingly informative mutations such as POLE/D1 mutations which are predictive of sensitivity to immunotherapies." (PMID 39456850, 2024). "POLE mutations are associated with high tumor mutation burden, which may trigger the immune system to recognize the cancer cells as foreign and mount a robust anti-tumor response." (PMID 38262245, 2024). "Therefore, further studies are needed to elucidate how POLE mutations regulate chemokine secretion from tumor cells and promote the invasion of immune cells in solid tumors." (PMID 38238314, 2024).
tumor (continued). "Additionally, the in vivo tumor growth analysis in huHSC-NCG humanized mice revealed that the POLE P286R mutation suppressed tumor growth, leading to reduced tumor size and weight." (PMID 38238314, 2024). "The combination of variants in the RET (rs587778656) and POLE (rs1064796427) genes could be involved in tumor development." (PMID 39273494, 2024). "Whether other POLE cancer mutant alleles could drive tumor progression in a similar manner is an important issue for future works." (PMID 37891003, 2024). "Furthermore, the POLE mutation suppressed the tumor growth of human EC cells in humanized immune mice by enhancing the infiltration and activation of cytotoxic T cells." (PMID 38238314, 2024). "Given these promising results, translating the use of neoadjuvant immunotherapy in pMMR tumors with microsatellite instability features conferred by high tumor mutation burden and POLE mutations offers other potential treatment possibilities; however, more research is needed." (PMID 39114842, 2024). "One case with BRAF wild type lost in vitro the POLE mutation demonstrated in the parental tumor." (PMID 39204387, 2024). "Described pathogenic POLE-EDM mutations in different tumor entities." (PMID 39239272, 2024). "POLE mutations may lead to DNA replication disorders and tumor hypermutation, making patients more likely to have high microsatellite instability." (PMID 39839672, 2024). "In conclusion, these results suggest that POLE mutations may impede tumor growth and trigger anticancer immune responses through the STING/TBK1/IRF3 signaling pathway." (PMID 38238314, 2024). "Indeed, the Refining Adjuvant treatment In EC Based On molecular features (RAINBO) phase II trial is randomising patients with POLE mutated tumours to de-escalation of adjuvant treatment after surgery even for stage III tumours (NCT05255653)." (PMID 37760602, 2023). "Around 1% of patients with pathogenic POLE mutations died of the tumor." (PMID 37874375, 2023). "However, it is important to highlight that the patient in the present report, in addition to colon PNs and concomitantly a NET, had undergone total thyroidectomy 8 years before an MTC, a multi-tumor phenotype presented in pathogenic mutations of the POLE gene." (PMID 36629684, 2023). "While they can occur in a broad range of cancers, spontaneous POLE mutations are particularly enriched in endometrial (9–10%) and colorectal (2–3%) cancers and their tumor mutation burdens (TMBs) are often in excess of 100 mutations per megabase, some of the largest found in all human cancers." (PMID 37388540, 2023). "The tumor mutation burden (TMB) was higher in ECs with POLE mutation." (PMID 38023184, 2023). "However, the immune infiltration and immunotherapy-related gene expression in the tumor microenvironment (TME) of POLE-mutated ECs remain unresolved." (PMID 38023184, 2023). "Our case highlights the significant therapeutic benefits that may arise from the presence of a pathogenic POLE mutation in a recurrent, metastatic colon cancer subject whose tumor was otherwise MSS." (PMID 37239414, 2023). "An EDM mutation in POLE was observed in the parental tumor and TG8-PDXs of case UXE-004." (PMID 37231035, 2023). "The tumor also present MMR deficiency with MSH6 loss inconsistent with the MSS status which may be a secondary event induced by the novel pathogenic POLE T278K mutation." (PMID 36765365, 2023). "Here, we aim to provide functional evidence, including tumor mutational burden and spectrum, functional assays and in silico structural analyses, together with updated segregation data that support pathogenicity for POLE c.1373A > T p.(Tyr458Phe)." (PMID 36856825, 2023).